KRAS (KRas proto-oncogene, GTPase)
Diseases named in the same sentence as KRAS in open-access papers (continued):
Sharing a sentence is not in itself a finding about the gene and the disease.
colorectal cancer (continued). "Moreover, majority of colorectal carcinomas exhibiting wild-type KRAS do not respond to such therapies either." (PMID 22931052, 2012). "KRAS codon 12/13 and 59/61 and BRAF V600E mutations, MSI, and MGMT and hMLH1 methylation and expression in 42 serrated adenocarcinomas and 17 serrated adenomas were compared with those in 59 non-serrated colorectal carcinomas (CRCs) and nine adenomas." (PMID 21457162, 2011). "Presence of KRAS mutations therefore represents a negative predictor of response to EGFR therapy and KRAS mutation testing has rapidly moved into the molecular diagnostic work-up of colorectal cancers considered for EGFR treatment." (PMID 19832985, 2009). "The oncogenes MAP2K2 and KRAS exhibited changes in isoform proportions, despite no significant alterations in their overall gene expression levels, which indicates that their distinct RNA isoforms may have different functions in colorectal cancer." (PMID 40702779, 2025). "For instance, since the concept that KRAS mutant colorectal cancer patients do not benefit from the addition of EGFR antibodies to the chemotherapy backbone was introduced, determination of RAS status has become part of the routine diagnostic workup in patients with advanced colorectal cancer." (PMID 34436668, 2022). "However, as anti-EGFR antibody treatment induces ADCP of human colorectal cancer cells by macrophages, independent of mutations in EGFR signaling pathways, mutations in KRAS or BRAF are not expected to negatively impact the efficacy of preoperative antibody treatment to eliminate CTCs." (PMID 35035479, 2022). "However, on the other hand, about 50% of patients with wild-type KRAS colorectal cancer may not respond to anti-EGFR therapies." (PMID 33946899, 2021). "Oncogenic KRAS drives an immune suppressive program in colorectal cancer by repressing interferon regulatory factor 2 expression, and may sensitize lung adenocarcinoma to GSK-J4-induced metabolic and oxidative stress; moreover, KRAS-targeted anticancer strategies have been documented." (PMID 33240468, 2020). "In addition, of 8 patients (colorectal cancer, n = 3; NSCLC, n = 1; endometrial cancer, n = 1; breast cancer, n = 1; ovarian cancer, n = 1; melanoma, n = 1) with KRAS G12 or G13 mutation in cfDNA, but not in FFPE tumor samples, 2 patients had KRAS Q61 mutations in FFPE." (PMID 25980577, 2015). "The combinatorial inhibition of KRAS and EGFR in patients with KRAS G12C advanced colorectal cancer, a disease where KRASi monotherapy was not approved, shows promise in ongoing clinical trials." (PMID 38668053, 2024). "It has indicated that statins during and after adjuvant chemotherapy in patients with colorectal cancer have been shown not to improve DFS, recurrence-free survival, and OS in KRAS mutant and wild-type patients." (PMID 37069612, 2023). "In one study, cell lines were generated from a patient with concurrent BRAFV600E-mutant melanoma and KRAS-mutant colorectal cancer, with paradox breakers inhibiting the BRAFV600E-mutant cells without paradoxically enhancing the growth of the KRAS-mutant cells." (PMID 33367512, 2021). "In another report, the same dual β1-integrin/EGFR inhibition approach, as well as KRAS or BRAF depletion and 5-FU-treatment failed to modulate the radiosensitivity of colorectal carcinoma cells." (PMID 32903756, 2020). "In this study we observed that MEK inhibition further induced canonical WNT signaling in APC and KRAS mutant HCT-15 colorectal cancer cells, but not in APC mutant/KRAS WT COLO320DM cells." (PMID 30717152, 2019).
colorectal cancer (continued). "The present study characterized the functional consequences of non-canonical/novel KRAS and NRAS mutants identified in a targeted next-generation sequencing study of colorectal cancer specimens from Filipino patients." (PMID 31816869, 2019). "The non-canonical/novel KRAS and NRAS mutants were also assessed for their potential to resist apoptosis in colorectal cancer cells." (PMID 31816869, 2019). "Here, we showed the antibiotic salinomycin (SAL) combined with GEF exerted synergistic cytotoxicity effects in colorectal cancer cells irrespective of their EGFR and KRAS status, with a relatively low toxicity to normal cells." (PMID 26461472, 2017). "Despite promising data, the clinical use of any biomarker in general practice is lacking, and currently only KRAS, BRAF and microsatellite instability are currently used in the diagnosis and treatment of colorectal cancer." (PMID 28125730, 2017). "In the present study, we showed that the combination of GEF and SAL was synergistic at decreasing cell viability, colony formation ability and inducing cell apoptosis in colorectal cancer cell lines irrespective of their EGFR and KRAS status." (PMID 26461472, 2017). "In patients with colorectal cancer, EGFR therapy-resistant KRAS mutant subclones support non-mutant therapy-sensitive cells by secreting increased levels of TGFalpha and amphiregulin, in turn sustaining EGFR/ERK signalling in sensitive cells." (PMID 28716075, 2017). "Patients with KRAS-mutant colorectal cancer do not benefit from EGFR-targeted therapy and outgrowth of KRAS-mutant cells accompanies onset of resistance." (PMID 27437872, 2016). "Retrospective data demonstrating a lack of response of patients with KRAS exon 2 mutant, and now extended RAS mutant, metastatic colorectal cancer to anti-EGFR therapy has changed the focus of colorectal cancer treatment to one of personalized cancer care." (PMID 26136684, 2015). "BCL2 family inhibitors, in combination with a TORC1/2 inhibitor, lead to apoptosis in KRAS- and BRAF-mutants but not wild-type (WT) colorectal cancer cells." (PMID 26636651, 2015). "Though the use of MEK inhibitors as single-agent therapy in colorectal cancer is not supported by these results, a recent phase II study of a MEK inhibitor combined with irinotecan in KRAS mutant CRC yielded interesting results worthy of further study." (PMID 26136684, 2015). "In addition, given that non-KRAS-mutated tumors include a distinct subset characterized by BRAF mutation, analyses were also performed to compare KRAS-mutated tumors with both BRAF-mutated tumors and the remaining subset of colorectal carcinomas, with observed neither somatic oncogene mutation." (PMID 25929517, 2015). "Mutations of the EGFR tyrosine kinase (TK) domains lead to constitutive kinase activation and were shown to be a good predictive marker in non-small cell lung cancer, while KRAS and BRAF were negative prognostic markers in colorectal cancer." (PMID 24932282, 2014). "In colorectal cancer, our model predicted that CMS4 tumors were not dependent on KRAS." (PMID 37141389, 2023). "However, the general strategy of targeting RAF dimerization in RAS/RAF mutant colorectal cancers is unlikely to qualitatively transform the outcomes with targeted therapies without appropriate attention to the unique biology of BRAF and KRAS mutant CRC." (PMID 32922659, 2020). "As the finding indicated that the efficacy of “cetuximab after oxaliplatin” was not restricted to the KRAS/BRAF wild-type background, the experiment was repeated using a panel of seven other colorectal cancer cell lines, representing variable KRAS/BRAF genotypes." (PMID 30410004, 2018). "We did not observe any significant association between overall or progression-free survival, neither when considering all colorectal cancer patients nor for subgroup analyses (metastatic, anti-EGFR [epidermal growth factor receptor] treatment, or KRAS wild type)." (PMID 24890702, 2014).
colorectal cancer (continued). "This is the first report of KRAS and BRAF status in Albanian patients with colorectal carcinoma (CRC) and though the relatively small sample size might not provide enough statistics power." (PMID 25267307, 2014).
lung cancer (2,414 papers, 1986 to 2026). A malignant neoplasm involving the lung. "Eligible studies evaluated the detection of KRAS mutations in ctDNA in plasma or serum for lung cancer diagnosis and reported sufficient data to construct 2 × 2 contingency tables." (PMID 41595170, 2026). "KRAS mutations are prevalent in lung cancer, but KRASG12C inhibitors exhibit limited efficacy, partly due to metabolic adaptations, such as enhanced glutathione (GSH) metabolism and increased glycolysis." (PMID 42240478, 2026). "Lung cancers showed typical non-small cell lung cancer (NSCLC) driver alterations (KRAS G12D, RET fusions, PIK3CA mutations) and pervasive tumor suppressor loss, with no microsatellite instability (MSI)-high cases." (PMID 41717185, 2026). "Lung cancer remains the leading cause of cancer-relatedmortality, and KRAS mutations are foundin approximately 32% of cases, renderingthis mouse strain a highly relevant model system to test the effectivenessof Deltafluorine in cancer." (PMID 41499451, 2026). "For example, in lung cancer patients with co-mutations of KRAS and LKB1, a high expression of G6PD is associated with a poor prognosis." (PMID 41328353, 2026). "Conclusions: ctDNA-based detection of KRAS mutations demonstrates high specificity but moderate sensitivity for diagnosing lung cancer." (PMID 41595170, 2026). "BACKGROUND: KRAS mutations are approximately 25% of human cancers, with particularly high incidence in breast and lung cancers, by constitutively triggering MAPK/ERK and PI3K/AKT pathways that advance proliferation, survival, and autophagy-mediated resistance." (PMID 41928324, 2026). "We also examined the requirement for STK11, a tumor suppressor and metabolic regulator frequently co-mutated with KRAS in lung cancer." (PMID 41892297, 2026). "Hu depicted that KRAS mutation impairs the macrophage phagocytosis sensitivity by increasing CD47 expression in lung cancer." (PMID 39806421, 2025). "In summary, we believe that radiomics demonstrates good diagnostic efficacy in predicting the KRAS mutation status in lung cancer." (PMID 41584578, 2025). "This study aimed to systematically evaluate the diagnostic performance of radiomics-based models in predicting KRAS gene mutations in lung cancer and quantitatively analyze the methodological quality and reporting standardization of related studies." (PMID 41584578, 2025). "KRAS is one of the most frequently mutated oncogenes in human cancers, particularly in pancreatic, colorectal, and lung cancers." (PMID 39806421, 2025). "In KRAS-mutated lung cancer, combining MEK with CDK4/6 inhibitors suppressed cell proliferation and enhanced NK cell-mediated immunosurveillance." (PMID 40557151, 2025). "In LKB1-deficient KRAS-mutant lung cancer cells treated with KRAS or MEK inhibitors, hyperactivation of JNK occurs due to loss of NUAK-mediated PP1B phosphatase activity." (PMID 40316540, 2025). "The FDA-approved therascreen KRAS assay, a companion diagnostic widely employed for colorectal and lung cancers, omits codon 61 mutation detection." (PMID 41514544, 2025). "This has been found true in other cancer types including pancreatic, colon and smoking related lung cancers, for which the incidence of KRAS codon 12 mutations is 90%, 50%, and 30% respectively." (PMID 40970185, 2025).
lung cancer (continued). "In this study, we introduce a novel micelleplex, named C14-PEI, designed to co-deliver Cas9 mRNA and sgRNA efficiently to excise the mutated KRAS allele in lung cancer cells." (PMID 39838780, 2025). "Our finding that LKB1 regulates the apoptotic dependency of KRAS-mutant lung cancers is unexpected, as genomic features associated with sensitivity to BH3 mimetics in oncogene-addicted solid tumors have been elusive." (PMID 40316540, 2025). "In this study, we utilized an anionic di-block co-polymer, PEG-PLE, to enhance the performance of lipid-modified PEI (C14-PEI) nanoplexes for delivering Cas9 mRNA and sgRNA targeting KRAS G12S mutations in lung cancer cells." (PMID 39687993, 2025). "In conclusion, this meta-analysis indicates that radiomics is a promising tool for determining the KRAS mutation status in lung cancer." (PMID 41584578, 2025). "For other prevalent actionable mutation in lung cancer KRAS, PIK3CA, FGFR3, MET, NRAS, and RET demonstrated 100 % specificity with varied sensitivities around 50 %." (PMID 40503459, 2025). "The study revealed that C14-PEI micelleplexes effectively co-deliver Cas9 mRNA and sgRNA for targeted genome editing of KRAS mutations in lung cancer cells." (PMID 39838780, 2025). "Radiomics models exhibit moderate diagnostic performance in predicting KRAS mutations in lung cancer." (PMID 41584578, 2025). "KRAS mutations were associated with higher combined positive score (CPS) values in cases with lung cancer." (PMID 41515496, 2025). "CRISPR-Cas9 has emerged as a highly effective and customizable genome editing tool, holding significant promise for the treatment of KRAS mutations in lung cancer." (PMID 39838780, 2025). "KRAS mutations are more common in male smokers with lung cancer, whereas EGFR mutations are more frequent in Asian female never-smokers with lung adenocarcinoma." (PMID 40890819, 2025). "By 8 weeks resistant lung cancer nodules develop which are FDG avid, but these resistant nodules are not adenocarcinoma (the classic histological subtype of human STK11-deficient/KRAS mutant lung cancer) but squamous cell carcinoma." (PMID 40069402, 2025). "KEAP1 deficiency also promotes the progression of KRAS-driven lung cancer and leads to its dependence on glutamine metabolism." (PMID 40083325, 2025). "KRAS‐derived mutations were found in 11.0% (28/255) of patients, with the highest prevalence in colorectal (18.6%, 11/59) and lung cancers (29.3%, 12/41)." (PMID 39748775, 2025). "This phenomenon aligns with the high incidence of lung cancer in China and the relatively elevated KRAS mutation rate in the Asian region." (PMID 41584578, 2025). "For instance, in lung cancer research, organoids have been instrumental in drug screening, leading to the discovery of Manoalide (MA) as an agent that sensitizes KRAS-mutated and osimertinib-resistant lung cancer to EGFR-TKIs." (PMID 40427552, 2025). "STK11/KRAS co-mutated lung cancer cells demonstrate increased glycolysis, and are more sensitive to glycolysis inhibition or glucose deprivation than either KRAS single mutant or STK11 single mutant cells." (PMID 40069402, 2025). "A recent case report has described complete disease remission of a KRAS-mutated brain oligometastatic lung cancer patient after immuno-chemotherapy with pembrolizumab." (PMID 40362343, 2025).